CD4 (CD4 molecule)
Diseases named in the same sentence as CD4 in open-access papers (continued):
Sharing a sentence is not in itself a finding about the gene and the disease.
tumor (continued). "It was suggested that CD4+ cells kill tumor cells through a mechanism that did not involve Fas/FasL or TNF-α, but was dependent on the TNF-α related apoptosis inducing ligand (TRAIL)." (PMID 31379821, 2019). "Consistent with lower immunosuppression as an important precondition to promote the induction of tumor-directed T-cell responses, we observed an increase in tumor-infiltrating CD8 T cells 10 days after therapy initiation and a modified CD8/CD4 ratio in favor of CD8 T cells." (PMID 31324774, 2019). "When compared to blood, the number of mutant-specific T cells may be enriched in IDH1R132H expressing tumor tissue in case an effective T cell response had occurred, providing a rationale to screen for the presence of IDH1R132H-specific CD4 T cells among TILs." (PMID 31240524, 2019). "In addition, we examined the level of CD4+, CD25+, and Foxp3+ in tumor regulatory T cells (Tregs) by flow cytometry on day 8 after the start of treatment." (PMID 31653838, 2019). "An upregulation of CD69 activation marker occurs for both CD4+ and CD8+ (Fig. 5AII) UniCAR T cells in a strict tumor-specific and TM-dependent manner, while the activation level of UniCAR T cells redirected by the His-tagged or un-tagged TM was indistinguishable." (PMID 31332252, 2019). "In a single region of interest, among other cell types, tumor cells (Keratin+), T-helper cells (CD3+CD4+), cytotoxic T cells (CD3+CD8+), regulatory T cells (CD3+FOXP3+), HLA-DR+ macrophages (CD68+HLA-DR+), CD163+ macrophages (CD68+CD163+), and CD11c+ macrophages (CD68+CD11c+), were identified." (PMID 31736961, 2019). "In addition, polyclonal CD4+ T cells from MHC-II-negative ovarian cancer tumor-bearing mice were able to secrete CCL5 and recruit CCR5+ DCs to the tumor." (PMID 31379821, 2019). "Further supporting results from statistical analyses, CD4+ clusters inside the lymph follicle showed overlapping areas with PD-L1 staining while being almost absent within the tumor (arrow heads)." (PMID 30899426, 2019). "CD4+CD25+CD127dim/− Tregs express high level of transcriptional factor FoxP3 and secrete interleukin (IL)-35/IL-10, and suppress activation and expansion of tumor-antigen-specific effector T cells to maintain peripheral tolerance in malignant cancers." (PMID 30988066, 2019). "In fact, mice depleted of neutrophils show no therapeutic benefit from BCG when compared to untreated controls, with an absence of CD4 T cell influx which is known to be essential to the anti-tumor response." (PMID 31824850, 2019). "Although a subset of the activated CD4+ T cells expressed forkhead box protein P3 (FoxP3) and appeared to be T regulatory cells (Tregs), these cells did not significantly impact the anti-tumor vaccine response." (PMID 30956760, 2019). "Examination of her tumor biopsy showed a CD4:CD8 ratio of 9:1 without aberrant T cell antigen expression." (PMID 30709425, 2019). "We identify predominant CD8+ T cell effector populations, Tregs, and resting (but not activated) CD4+ T cells in datasets derived from diverse tumor types (breast, lung, skin, colon)." (PMID 31624246, 2019). "We hypothesize that presentation of tumor-specific antigens by mature MHCII+ dendritic cells mediates the activation and stimulation of Th17 CD4+ T cells, which become the main driver of tumor growth delay." (PMID 31362778, 2019). "We showed that the proportion of CD4+CD25+ Tregs in lymphocytes increased significantly after co-culture, and Foxp3, NRP1 and CTLA-4 expression on the surface of the cells were upregulated, indicating that the tumor cells stimulated T cell immune responses." (PMID 31417646, 2019). "In the 4-nitroquinoline 1-oxide-induced malignant oral/esophageal injury model, exosomes carrying PD-L1 isolated from supernatants of murine or human HNSCC cell lines can hamper the infiltration of CD4+ T and CD8+ T cells into the tumor microenvironment, thereby accelerating tumor progression." (PMID 31647023, 2019).
tumor (continued). "We also found that tumor‐infiltrating CD4+ and CD8+ T cells were more abundant after combination therapy, particularly in the distant tumor, which correlated with the presence of more IFN‐γ in the tumor microenvironment, but the ratio of CD8+/CD4+ T cells was not changed by the combination therapy." (PMID 31453050, 2019). "Thus, THP1-FRβ tumor-bearing mice were engrafted with a research batch of EGFRt-unsorted E2-CAR-T cells (~23% EGFRt+, 1:1 CD4:CD8) at ~6 million/animal and then treated with 3 different EC17 dosing regimens." (PMID 30941303, 2019). "The chlorine e6 and doxorubicin-loaded hollow manganese dioxide nano platform (H-MnO2-PEG/C&D) can relieve tumor suppression whereas checkpoint-blockade (PD-L1 blockade) promotes the higher TNF-α secretion and augmented CD4+ and CD8+ T cells-mediated immune response than chemo-PDT therapy." (PMID 31754376, 2019). "CD4+ helper T lymphocytes react to CAF secretion of CCL2, CCL5, and CCL17 along with polarizing cytokines IL-1, IL-6, IL-13, and IL-26 by switching from an anti-tumor TH1 response to a pro-tumor TH2 and TH17 response." (PMID 31058816, 2019). "Thus, it appears that neutrophils mediate the influx of later immune mediators of the anti-tumor BCG response such as monocytes and CD4 T cells." (PMID 31824850, 2019). "Downregulation of c-FLIPL and PD-1 therapy alone could increase the CD8+/CD4+ ratio to a similar degree, however, the percentage of CD8+ T cells appear to be increased to a greater extent in B16- c-FLIPL-shRNA tumor groups." (PMID 31552181, 2019). "Notably, cDC1-based vaccines enhance tumor infiltration by cancer-reactive CD8+ and CD4+ T cells and halt progression of engrafted cancer models, including tumors that are refractory to anti-PD-1 treatment." (PMID 30961656, 2019). "We next investigated whether tumor growth delay in the unirradiated tumors was mediated by immune activation by analyzing the expression of CD8+/GzmB+ cells and CD4/Foxp3+ cells in TILs by flow cytometry." (PMID 30774761, 2019). "Immunohistochemistry demonstrated IL-10 expression by CD4+CD25+ T cells, but not by tumor associated macrophages or DCs." (PMID 31681327, 2019). "As opposed to the sole purpose of CD8+ T cells at the tumor site, the multifaceted and wide-ranging role of CD4+ T cells potentially makes CD4+ a better target for following T cell activity by PET imaging." (PMID 31754392, 2019). "Significantly higher CD69 levels, in both CD4+ and CD8+ cell populations, were observed in the HPK1 KD group in comparison with WT group, indicating that HPK1 KD leads to augmentation of T cell activation in the tumor bearing mice." (PMID 30913212, 2019). "Emergence of certain myeloid subsets in the spleen, such as CD44+MDSCs and IL-17A+MDSC were associated with advanced cancer, while within the lymphoid subsets, the absence the B220+ B-cells, CD62L+ B-cells, CD62L+CD4+ T-cells, and CD62L+ CD8+ T-cells was shown in the untreated tumor bearing mice." (PMID 31881770, 2019). "However, they demonstrate differences in the effector functions of CD4+ and CD8+ CAR subsets and improved anti-tumor effects when combining both subsets." (PMID 31332252, 2019). "Similarly, Dex derived from DCs loaded with lysates from chaperone-rich cells (CRCLs) and GL261 murine glioblastoma tumor cells induced proliferation and CTL activity of CD4+ and CD8+ T cells and enhanced the production of IL-2 and IFN-γ in vitro." (PMID 31615107, 2019). "Both CD4+ and CD8+ T cells isolated 3 weeks post inoculation secreted less IFNγ than CD4+ and CD8+ T cells isolated 2 weeks after tumour inoculation, whether T cells were PD-1+ or PD-1-." (PMID 31277636, 2019). "Also, HLA-1 low-expressing tumor areas appeared to frequently be surrounded by a greater number of CD4+FOXP3+ (regulatory T cells) and a lower number of CD68+ (likely macrophages) immune cells relative to HLA-1 high-expressing tumor regions of the same TME." (PMID 31166985, 2019).
tumor (continued). "Salmonella replication and the lysis of tumor cells could increase the infiltration of CD4+ T cells and CD8+ T cells to enhance immune responses to tumor cells." (PMID 31598148, 2019). "Besides, CD19+CD25hi Bregs inhibit the proliferation of CD4+ T cells by secreting IL-10 and TGF-β and promote the expression of FoxP3 and CTLA-4 in the Tregs, both of which are Tregs tumor suppressor markers." (PMID 31662750, 2019). "The administration of anti-CD4 antibodies had a moderate effect on the vaccination apparent from a slightly larger initial tumor formation and with 3 out of 7 mice that were no longer protected and developed slow growing tumors." (PMID 30858929, 2019). "In fact, higher numbers of CD8+ cells could be observed per gram of tumor tissue, whereas FOXP3−CD4+ and FOXP3+CD25+CD4+ Tregs cells decreased." (PMID 31046839, 2019). "A positive correlation was found between the numbers of tumor-infiltrating CD8–Foxp3+Tbet+ Tregs, CD8–Foxp3–Tbet+ (CD4) T cells and CD8 + Foxp3–Tbet+ T cells, supporting the notion that CD8–Foxp3+Tbet+ Tregs accumulate at similar sites as type 1-oriented (Foxp3-) effector T cells." (PMID 30658697, 2019). "These include direct effects on tumor cells by cytokines produced by CD4+ T cells such as IFN-γ, TNF-α, and IL-2, modulation of DCs and other antigen presenting cells in the tumor microenvironment as well as direct killing of tumor cells by cytolytic CD4+ cells." (PMID 31379821, 2019). "Previously, cryo-thermal-induced M1 macrophage polarization was exclusively responsible for the subsequent DC maturation, differentiation of CD4-CTL and Th1 subsets, which was crucial for mediating long-term anti-tumour memory immunity after cryo-thermal therapy." (PMID 31519961, 2019). "Further, deletion of the bulk CD4+ T cell population allowed for long-lived antigen-specific CD8+ T cells in secondary lymphoid organs and were protective after primary tumor resection against both localized and systemic secondary tumor challenges." (PMID 31379821, 2019). "The role of cDC2s in anti-tumor immunity is far less clear outside of their potential role to activate CD4+ T cells through TH2 differentiation and may be involved in regulating multiple aspects during tumor development." (PMID 30991681, 2019). "Therefore, we assessed the frequency of different tumor infiltrating immune cell subsets including Tregs, MDSCs, TAMs, CD8 cells and CD4 effector T cells by flow cytometry analysis." (PMID 31015520, 2019). "We also observed that the CD3+CD4+ T cells but not CD3+CD8+ T cells were decreased in the blood of the AMPKα2−/− tumour‐bearing mice." (PMID 30636376, 2019). "Additionally, CD4 + CD25 + Treg cells secrete TGF-β and IL-10 to suppress effector T cells such as CD8 + cytotoxic T lymphocytes infiltrating the tumor into HCC secreting anti-tumor effector molecules such as IFN -γ, IL-2 and TNFα." (PMID 31600917, 2019). "Expressions of PD‐L1 and PD‐L2 were predominantly in tumor‐infiltrating lymphocytes and showed significant negative correlations with CD4+ or CD8+ infiltrates, respectively." (PMID 31657115, 2019). "Though tumor-infiltrating DNT cells expressed PD-1, they were the least frequent PD-1+ T cell subset and showed the most variability in PD-1 expression compared to CD4+ and CD8+ T cells (CD4: 65.8 ± 7.1%, CD8: 67.2 ± 7.2%, DNT: 55.5 ± 11.7%)." (PMID 30857561, 2019). "We also evaluated CD204+ CD4+ macrophages and found no significant change in the CD204+ CD4+ area in the tumor of patients receiving two doses of 1.0 mg/kg IT1208." (PMID 31340866, 2019). "The tumour cells escape immunological surveillance by diminished recognition by immune cells through CD8+, CD4+ T cells and natural killer (NK) cells; the increased resistance by tumour cells; or the instigation of an immunosuppressive microenvironment via regulatory T cells (Tregs) and cytokines." (PMID 30893948, 2019).
tumor (continued). "It has been proposed that they act via the expression of the transcription factor STAT3, whereby they produce cytokines to promote a tumor-supportive environment by suppressing the proliferation of anti-tumor CD4+ and CD8+ T cells and promoting the activity of regulatory CD4+ T cells." (PMID 31815646, 2019). "Consistent with CD8-independent and -dependent target cell recognition by 19305DP and CD8SP, respectively, 19305DP-TCR but not CD8SP-TCR provided efficient tumor-recognizing ability to CD4+ T cells." (PMID 30626427, 2019). "Our results showed that YFTL could increase the percentages of the three cells and the up-regulated ratios of the CD4+ T cells, CD8+ T cells, and NK cells might participate in the anti-tumor activity of YFTL in vivo." (PMID 30781674, 2019). "Together, our results indicate that the naturally occurring 19305DP-TCR derived from CD4+CD8+ double-positive αβ T cells, is a promising therapeutic TCR gene for effective and safe adoptive T-cell therapy in A*02+ patients with NY-ESO-1-expressing tumor." (PMID 30626427, 2019). "We noted a CD4:CD8 inversion (CD4:CD8 < 1:2) in 5/41 (12%) cases without signs of tumor cell destruction." (PMID 31766212, 2019). "Patients with negative E-Cad expression had less CD4+/PD-1− TILs in tumor microenvironment than those with positive E-Cad expression." (PMID 30069490, 2018). "Immune cells in the tumor environment may either activate CD4 helper and CD8 cytotoxic T lymphocytes in an MHC I and MHC II dependent manner or promote tumor growth in the presence of infiltrating leukocytes." (PMID 30159133, 2018). "However, elderly tumor-bearing mice demonstrated reduced MHC-I, MHC-II and CD80 on CD11c+ cells, and decreased IFN-γ by CD8+ and CD4+ T cells within tumors, compared to young counterparts, implying loss of function." (PMID 30560130, 2018). "Furthermore, a significant correlation was observed between the percentages of CD3 + PD-1+, CD3+ CD4+ PD-1+ or CD3+ CD4+ CD25+ FOXP3+ PD-1+ lymphocytes in PBMCs and the level of PD-L1 expression detected by IHC in tumor tissue (p < 0.05)." (PMID 30546030, 2018). "Although CD4+ T cells are classically viewed as helper cells facilitating CD8+ T cell function, it is now clear that both cell subsets can exert cytotoxicity against tumor targets." (PMID 30233577, 2018). "This elevation was also found in CD4+ T cells isolated from BALF in tumor site rather than in nontumor site (approximately ten-fold induction, P<0.0001)." (PMID 30473538, 2018). "Additionally, the induction of effective CD4 helper responses are crucial for improved CD8 T-cell priming and memory formation, increased tumor infiltration, and local effectiveness." (PMID 29755468, 2018). "CD4+ and CD8+ T lymphocytes have been shown to target epitopes arising from epigenetic, transcriptional, translational, and post-translational alterations of tumor cells." (PMID 28108950, 2018). "Moreover, activated CD4+ and CD8+ T cells and natural tumor killer cells were induced in tumors resulting in significant tumor growth reduction and prolonged survival." (PMID 29883422, 2018). "Comprehensive flow cytometry analysis was performed to corroborate confocal imaging findings on immunogenic tumor cell death (LIVE/DEAD viability markers and cleaved caspase 3) and TIL activation (CD25, CD69, Ki-67 and granzyme expression in CD4 and CD8 positive lymphocytes)." (PMID 30400822, 2018). "The reduction in recruitment of CD4+ and CD8+ T cells in the TME is a reflection of T cell populations in the periphery, as seen by analysis of immune cells in the spleen and blood of non-tumor bearing mice." (PMID 30237863, 2018). "Moreover, forced expression of PD-L1 and CD47 upon Myc inactivation was correlated with worse antitumor immune response as indicated by the reduction of macrophages and CD4 + T cells in TME, tumor progression, and maintenance of angiogenesis and senescence." (PMID 29765155, 2018).
tumor (continued). "Conversely, sunitinib treatment significantly reduced the magnitude of Tregs (CD4+CD25+FoxP3+) from 10% in control tumor-bearing mice without treatment to 7%, and MDSCs (CD11b+Gr-1+) from 1.1% to 0.7%." (PMID 30123861, 2018). "The expression of T-bet with the B7H6-specific CAR in CD4+ T cells conferred higher expression of the CAR, elevated secretion of Th1 and proinflammatory cytokines, and improved cellular cytotoxicity against B7H6-expressing tumor cells." (PMID 29515240, 2018). "Based on the immune score assigned to each cell type, B-cells, CD4+ T cells and NK cells were absent in the tumour environment, while CD8+ T cells, monocytes, M1 and M2 macrophages were present." (PMID 30108227, 2018). "CD4+CD25+ Treg cells have been proposed to maintain the body's immune tolerance and prevent an immune response to homologous tumor cells, thereby playing a crucial role in tumor development." (PMID 30517305, 2018). "Indeed, studies in mouse tumor models show that antiCTLA-4 expands effector CD4+ T cells and anti-PD-1 antibody “reinvigorates” exhausted-like CD8+ T cells within the tumor microenvironment." (PMID 30376867, 2018). "Although CD4 and CD8 T cell responses to cancer have been extensively described, it is still poorly understood how regulatory mechanisms and crosstalk between T lymphocyte subsets influence tumor immunity." (PMID 29032503, 2018). "Total cell counts across whole tumor sections were performed to determine immune-to-tumor cell ratio; CD8+, CD4+, and CD20+ lymphocytes increased 10-fold, 3-fold, and 2-fold, respectively, in the SC mts with respect to the primary tumor, while Foxp3+ cells were scarce." (PMID 29774030, 2018). "The CVD915 strain was evaluated in a breast cancer murine model, and it delayed tumor growth in association with CD8+ and B220+ lymphocyte activation, but not CD4+ cells." (PMID 30302344, 2018). "The percentages of CD4+, CD8β+, and perforin+CD8β+ T cells in peripheral blood did not reveal any difference between tumor bearing and non-tumor bearing pigs." (PMID 29930558, 2018). "Similarly, in tumor, the increased percentage of CD3+, CD4+ or CD8+ T cells was also observed in three treatment groups compared with the control group (each treatment P < 0.05 for each T cell, respectively, n = 6)." (PMID 29317734, 2018). "Redistributes CD4 and CD8 T cell content in spleen and tumor, and induce activation of T cells." (PMID 30400822, 2018). "Notably, pIL-12 GET recruited abundance of CD4+ T cells, CD8+ T cells and modified their function within the tumor microenvironment." (PMID 30544810, 2018). "Nonetheless, although venushigh CD8+ T-cells were detected in mice receiving anti-PD-1, anti-CTLA-4, the anti-PD-1/4-1BB combination or anti-CD4 mAbs, tumor growth was still not controlled in the anti-CTLA-4 group." (PMID 29348598, 2018). "Our study shows that the absence of IL-33 signaling affects the recruitment of CD4+ T cells, dendritic cells, macrophages, and NK cells to the tumor microenvironment." (PMID 30112116, 2018). "In contrast, the lack the CD4+ TH cells had a moderate effect on tumor growth, but not on metastasis." (PMID 30237863, 2018). "The major alteration identified was a significant increase in the density of CD8+ cells, but not CD4+, in T1 tumours from ApcMin/+Lect2−/− mice, the stage significantly decreased in this model." (PMID 30559928, 2018). "Interferon production in CD4+ and CD8+ gated cells, cytotoxicity rates of target cells and mice survival were all significantly greater in this group than in controls, and all the mice in this group were tumour‐free throughout the experiment." (PMID 28944998, 2018). "Syngeneic T/SA tumour cells were used for this, which were infected with FP recombinants that expressed CIITA-induced MHC-II molecules, for better presentation of the relevant viral protein peptides to the CD4+ T cells." (PMID 29385169, 2018).